CCR2 (C-C motif chemokine receptor 2)
Diseases named in the same sentence as CCR2 in open-access papers (continued):
Sharing a sentence is not in itself a finding about the gene and the disease.
cerebral aneurysms (1 paper, 2025). "Non-selective inhibitor of CCR1 and CCR2, capable of reducing BP, increasing blood flow, and reducing arterial wall thickness in SHR animals; In C57BL/6 mice, it was able to reduce the formation of cerebral aneurysms." (PMID 40859641, 2025).
cerebral malaria (1 paper, 2023). A sequestration of Plasmodium falciparum in the brain, which can cause coma and/or seizures. "However, future analysis is necessary to confirm or investigate this hypothesis, mainly by evaluating the production levels of CCL2, CCL4, CXCL4, CXCL8, CXCL10, and the receptors CXCR3 and CCR2, correlated with susceptibility to cerebral malaria and lung inflammation." (PMID 38256880, 2023).
Chagas disease (1 paper, 2021). A parasitic infection caused by Trypanosoma cruzi. "In the present work, we first determined the spontaneous expression of pro-inflammatory mediators, such as MCP-1 and its receptor CCR2, and IL-12, TGF-β, IL-6 in cultured PBMC from seropositive patients with different clinical forms of Chagas disease." (PMID 35360222, 2021). "The results show that PBMC from Chagas disease patients display higher levels of IL-12, TGF-β, IL-6, MCP1, and CCR2 than cells from uninfected individuals (HI), irrespectively of the clinical stage, asymptomatic (Asy) or with Chagas heart disease (CHD)." (PMID 35360222, 2021). "Further case control studies, namely, cohorts of fenofibrate vs. placebo treated patients, are needed to test the hypothesis that fenofibrate restores the percentage of CCR2+ non-classical monocytes leading to improvement of ventricular function in patients with Chagas disease." (PMID 35360222, 2021).
chlamydial infections (1 paper, 2025). "Specifically, ccr2 deficiency disrupts the differentiation and response of Th1 cells, which are the primary effector lineage responsible for clearing chlamydia through secretion of interferon-gamma (IFN-γ)." (PMID 39903705, 2025).
cholangiocarcinoma (1 paper, 2025). A carcinoma that arises from the intrahepatic biliary tree (intrahepatic cholangiocarcinoma) or from the junction, or adjacent to the junction, of the right and left hepatic ducts (hilar cholangiocarcinoma). "The transcription factor EHF recruits and activates TAMs via the CCL2/CCR2 axis, remodeling the TME, and serves as a potential prognostic biomarker in cholangiocarcinoma." (PMID 41417432, 2025).
Cholestatic liver disease (1 paper, 2020). "In conclusion, Cholangiocyte-derived exosomal H19 played a critical role in macrophage activation, differentiation, and chemotaxis through CCL-2/CCR-2 signaling pathways, which represent a therapeutic target for cholestatic liver diseases." (PMID 31940841, 2020).
chondrosarcoma (1 paper, 2020). A malignant cartilaginous matrix-producing mesenchymal neoplasm arising from the bone and soft tissue. "A previous study revealed that in chondrosarcoma, the MCP-1/CCR2 axis requires c-Raf, MEK, ERK signal pathways for MMP-9 overexpression." (PMID 33228783, 2020).
Chronic colitis (1 paper, 2020). A chronic inflammatory disease of the large intestine (colon, cecum and rectum). "Murine colon macrophages are important mediators of tolerance to the intestinal microbiota, with their depletion by removing Ccr2+ monocyte precursors resulting in increased susceptibility to chronic colitis." (PMID 32117307, 2020).
chronic granulocytic leukemia (1 paper, 2023). "Secretory CYTL1 enhances MAPK/ERK pathway activation through C-C chemokine receptor type 2 in chronic granulocytic leukemia (CMML) (CCR2)." (PMID 37745303, 2023).
chronic granulomatous disease (1 paper, 2014). Chronic granulomatous disease (CGD) is a rare primary immunodeficiency, mainly affecting phagocytes, which is characterized by an increased susceptibility to severe and recurrent bacterial and fungal infections, along with the development of granulomas. "Thus, CCR2+Mo and their derivatives contribute to ROS-dependent mechanisms that are implicated in human defense against Aspergillus sp., i.e. the susceptibility of patients with chronic granulomatous disease to IA." (PMID 24586155, 2014).
chronic headache (1 paper, 2024). "In a mouse model of chronic migraine, we have found that the peripheral C-C motif ligand 2 (CCL2), C-C motif chemokine receptor 2 (CCR2) and CGRP signaling pathways interact with each other and play critical roles in the development of chronic headache-related behavioral and cellular sensitization." (PMID 39528947, 2024).
chronic kidney failure (1 paper, 2014). "Disease pathway analysis showed IL6, EPO, ADIPOQ and CCR2 to be involved in chronic kidney failure." (PMID 25280384, 2014).
ciliopathy (1 paper, 2023). A genetic disorder of the cellular cilia or the cilia anchoring structures, the basal bodies, or of ciliary function. "Upstream:Low expression of ciliary module composed of LKB1 in PTECsDownstream:accumulation of CCR2+ mononuclear phagocytes; promoting a ciliopathy phenotype." (PMID 38260142, 2023).
colorectal tumours (1 paper, 2022). "CCR2 and FPR1 are overexpressed in colorectal tumours, while Bacteroidales are enriched in CRC and associated with tumorigenesis." (PMID 35577971, 2022).
congenital toxoplasmosis (1 paper, 2024). Toxoplasma infection that is present from birth. "Taken together, inflammatory monocytes are important for protection against abnormal pregnancy in CCR2-deficient mice infected with T. gondii, indicating their therapeutic potential for congenital toxoplasmosis." (PMID 39051675, 2024). "Given that CCR2-deficient mice are a valuable model of abnormal pregnancies caused by T. gondii infection, it is hoped that the mechanism underlying congenital toxoplasmosis will be further explored using this model, and novel therapeutic strategies may be uncovered." (PMID 39051675, 2024). "In this study, we used CCR2-deficient mice with a C57BL/6 genetic background to assess the protective role of CCR2 in the pathogenesis of congenital toxoplasmosis." (PMID 39051675, 2024). "However, details of the role of CCR2 in the host immune response to T. gondii in congenital toxoplasmosis remain unclear." (PMID 39051675, 2024). "However, the role of CCR2 in congenital toxoplasmosis remains unclear." (PMID 39051675, 2024).
coronary artery calcification (1 paper, 2010). Calcification of the coronary artery, used as a measure of coronary atherosclerosis, a risk factor for myocardial infarction. "In our previous study the extent of coronary artery calcification was significantly lower in subjects with the CCR2 Ile64 variant than in subjects carrying two Val64 alleles suggesting a beneficial effect for the Ile64 allele." (PMID 20181074, 2010). "The extent of coronary artery calcification was found to be significantly lower in subjects with the CCR2 Ile64 variant than in subjects carrying two Val64 alleles which we interpreted as being beneficial." (PMID 20181074, 2010).
cutaneous T-cell lymphoma (1 paper, 2024). "This potential is exemplified by the ability of a small molecule inhibitor for CCR2 (CCR2i) to maximize the efficacy of PD-1 blockade in a murine model of a cutaneous T-cell lymphoma (CTCL)." (PMID 38275876, 2024).
cystic kidney disease (1 paper, 2023). A congenital or acquired kidney disorder characterized by the presence of renal cysts. "We also identified Cx3cr1 as a gene that governs cortex specific accumulation of Ccr2+ KRM and show that loss of Ccr2+ KRM reduces the severity of cystic kidney disease in a mouse model where cysts are mainly localized to the kidney cortex." (PMID 37256130, 2023).
cysticercosis (1 paper, 2017). "Our study shows that during experimental cysticercosis, Ly6Chi monocytes are recruited into the peritoneal cavity in a CCR2-dependent manner giving rise to AAMφs expressing PD-L2 and MR." (PMID 28094319, 2017).
diabetic macular edema (1 paper, 2023). "With respect to ocular inflammatory disease, a recent clinical trial tested a dual CCR2/CCR5 antagonist for treating diabetic macular edema; however, the results of the phase 2 clinical trial showed that this treatment was inferior to currently approved treatments." (PMID 37903056, 2023).
dry mouth (1 paper, 2022). "Co-expression levels of PD-1, CXCR5, CD4, CCR2, and CCR5 in the salivary gland specimens from patients with pSS and patients with dry mouth and eyes but normal pathology were also analyzed." (PMID 35755031, 2022).
ductal carcinoma in situ (1 paper, 2022). "•CCR2 and MET signals alter metabolism of ductal carcinoma in situ in animal models." (PMID 35405500, 2022).
echinococcosis (1 paper, 2026). A parasitic infection caused by tapeworm larvae of Echinococcus. "Our findings provide a mechanistic rationale for repurposing CCR2 antagonists as a novel host-directed therapeutic strategy for echinococcosis." (PMID 42057202, 2026).
Giardia infection (1 paper, 2019). "To determine if the macrophages described in this study represent an expansion of resident cells rather than the recruitment of blood monocytes to the intestine, we assessed macrophage accumulation during Giardia infection using CCR2-deficient mice." (PMID 31455692, 2019). "Collectively, these data indicate that CCR2 expression is not required for macrophage accumulation or parasite clearance during Giardia infection." (PMID 31455692, 2019).
glomerular diseases (1 paper, 2025). "CCL2, also known as macrophage chemokine-1 (MCP-1), is involved in the development of glomerular diseases by facilitating the recruitment of macrophages via interaction with type 2 C-C chemokine receptor (CCR2)." (PMID 40103820, 2025). "The glomerular expression levels of CCL2 and its receptor CCR2 were found to be elevated in human glomerulopathies, and CCL2/CCR2 signaling may mediate the development of a variety of glomerular diseases." (PMID 40103820, 2025).
gout (1 paper, 2024). A condition characterized by painful swelling of the joints, which is caused by deposition of urate crystals. "Similarly, CCR2 may also play an important role in the inflammatory response of gout via regulating the migration and activation of immune cells." (PMID 39677038, 2024).
Guillain-Barre syndrome (1 paper, 2014). A spectrum of rare post-infectious neuropathies that usually occur in otherwise healthy patients. "Chemokine ligand/receptor pair CCL2/CCR2 has been pathogenically implicated in the acute inflammatory demyelinating polyradiculoneuropathy variant of Guillain-Barré syndrome (GBS)." (PMID 24632828, 2014).
H1N1 virus infection (1 paper, 2017). "Characterization of inflammatory cell types in mice lung showed that overexpression of CCL2 and CCR2+ monocyte-derived cells (monocyte-derived dendritic cells and exudate macrophages) are the predominant cause of immune pathology during PR8/H1N1 virus infection." (PMID 28558796, 2017).
haemorrhagic stroke (1 paper, 2023). "CCR2 signalling therefore appears to be a common mechanism by which myeloid cells are recruited to the brain following ischaemic and haemorrhagic stroke." (PMID 36346451, 2023).
hematoma (1 paper, 2022). A hematoma is a collection of blood from a vascular structure into an extravascular space. "CCL2/CCR2 deficiency might decrease hematoma size at early time points but delay the recovery." (PMID 36704330, 2022). "At early times, CCL2/CCR2 deficiency might decrease hematoma size but delay long-term recovery." (PMID 36704330, 2022).
hepatitis B (1 paper, 2023). "Propagermanium has been used as a drug to treat hepatitis B and has been reported to inhibit CCR2." (PMID 36768216, 2023).
HIV-associated neurocognitive disorder (1 paper, 2021). HIV-associated neurocognitive disorder (HAND) remains a common complication of HIV infection in the combination antiretroviral therapy (ART) era. "An additional study assessed HIV DNA levels in PBMCs and found a correlation with CCR2 expression on intermediate monocytes and HIV-associated neurocognitive disorder (HAND)." (PMID 33914710, 2021).
Hyperammonemia (1 paper, 2022). An increased concentration of ammonia in the blood. "We also analyzed if the increased levels of BDNF and TrkB activation were due to the enhanced activation of the TNFR1–SP1PR2–CCL2 (monocyte chemoattractant protein-1)–CCR2–BDNF–TrkB pathway in hyperammonemia." (PMID 36233065, 2022). "Hyperammonemia increased the content of gephyrin and the phosphorylation of the β3 subunit of GABAA receptor in the cerebellum; these increases were reversed by blocking TrkB with ANA12, TNFR1 with R7050, S1PR2 with JTE-013, or CCR2 with RS504393." (PMID 36233065, 2022). "Hyperammonemia increased the content of the GABA γ2, α2, and β3 subunits, which were completely reversed by blocking TrkB with ANA12, TNFR1 with R7050, S1PR2 with JTE-013, or CCR2 with RS504393." (PMID 36233065, 2022). "We show here that the hyperammonemia-induced changes in GAD65 and GAD67, and in the membrane expression of GAT3, and of the γ2, α2, and β3 subunits of GABAA receptors are also reversed by blocking TNFR1 signaling, S1PR2, or CCR2." (PMID 36233065, 2022).
Hyperkeratosis (1 paper, 2013). Hyperkeratosis is a histopathological term defining a thickened stratum corneum and may be present in many different skin conditions, with many possible overlaps. "CCR2−/− mice injected with IL-23 display many of these same characteristics – epidermal acanthosis, hyperkeratosis and a mixed dermal inflammatory infiltrate." (PMID 23472158, 2013).
hypertensive nephropathy (1 paper, 2022). Kidney damage that results from chronically elevated blood pressure; complications include glomerular damage resulting in proteinuria and hematuria. "Previous study has shown that CCR2 activation plays an important role in the development of hypertensive nephropathy via increased oxidative stress and inflammation." (PMID 35725391, 2022).
hypertriglyceridemia (1 paper, 2023). A laboratory test result indicating elevated triglyceride concentration in the blood. "In HIV-infected patients with hypertriglyceridemia, fenofibrate regulates chemokine gene expression in circulating leukocytes, thereby reducing the expression of C-C motif chemokine receptor 2 (CCR2) and C-X3-C motif chemokine ligand 1 (CX3CL1) to mitigate inflammatory responses." (PMID 36724021, 2023).
intestinal tumours (1 paper, 2020). "The positive expression of MCP‐1 and CCR2 in intestinal tumours was enhanced by HFD supplementation." (PMID 31957197, 2020). "Hence, these data strongly proved the close relationship between the HFD‐induced dysbiosis and MCP‐1/CCR2 axis in the progression of intestinal tumours." (PMID 31957197, 2020).
kidney cancer (1 paper, 2024). Primary or metastatic malignant neoplasm involving the kidney. "Thus, the CCL2/CCR2 signalling pathway emerges as a promising avenue for therapeutic exploration in the context of kidney cancer, warranting dedicated research." (PMID 39011666, 2024).
Liver abscess (1 paper, 2022). A circumscribed area of pus or necrotic debris in the liver. "After selective depletion of KCs with clodronate liposomes or inhibition of monocyte infiltration with CCR2−/− mice, KCs, and inflammatory Ly6Chi monocytes were found to aggravate amebic liver abscess." (PMID 36169259, 2022).
lower respiratory tract infections (1 paper, 2022). "Under certain circumstances, such as lower respiratory tract infections, blood monocytes infiltrate the alveolar niche, through a CCR2-mediated mechanism and differentiate into fully functioning AM45,46." (PMID 36433992, 2022).
lumbar disc herniation (1 paper, 2017). "Our results are in agreement with others, showing that single intracisternal injections of CCR2 antagonist reduced neuropathic pain induced by inferior alveolar nerve transection and lumbar disc herniation." (PMID 28337574, 2017).
lung neoplasm (1 paper, 2011). A benign or malignant, primary or metastatic neoplasm involving the lungs. "Overall from previous and current tumor analyses using different dosing regimens, carcinogens, and strains of mice, a panel of common transcripts (e.g. Arg1, Areg, Ereg, Ccr2, Cdkn1a, Gja1, Ptgis, Spp1) may provide a useful tool for early diagnosis of lung neoplasm." (PMID 22039513, 2011).
lymphadenitis (1 paper, 2024). Acute or chronic inflammation of one or more lymph nodes. "Because disruption of IFN-γ signaling causes abnormal responses to BCG,46–48 and three CCR2-deficient patients (P1, P3, and P9) developed lymphadenitis or disseminated BCG disease following BCG vaccination, we evaluated IFN-γ-mediated immunity." (PMID 38157855, 2024).
Lymphadenopathy (1 paper, 2016). Enlargement (swelling) of a lymph node. "By further comparing the differences between antagonist and knockout models, it was evident that CCL2/CCR2 antagonists did not improve splenomegaly, lymphadenopathy, and circulating total/autoantibodies, suggesting the local involvement of CCL2/CCR2 in autoimmune target tissues, such as the kidney." (PMID 27403037, 2016).
Miscarriage (1 paper, 2024). A pregnancy that ends at a stage in which the fetus is incapable of surviving on its own, defined as the spontaneous loss of a fetus before the 22th week of pregnancy. "CCR2-deficient mice present with a lack of Tregs in the placenta, which may result in miscarriage." (PMID 39051675, 2024).
Mitral regurgitation (1 paper, 2024). An abnormality of the mitral valve characterized by insufficiency or incompetence of the mitral valve resulting in retrograde leaking of blood through the mitral valve upon ventricular contraction. "In a mouse model of atrial disease combining hypertension, obesity, and mitral regurgitation, more changes in atrial myeloid cells compared to ventricular cells were observed, with elevated numbers of CCR2+ macrophages and monocytes." (PMID 38391924, 2024). "Immunofluorescence histology was subsequently used on the left atrial appendages of 108 AF patients with mitral regurgitation and 41 sinus rhythm controls, and it was observed that atrial macrophages and monocytes originated in the greatest proportion from the CCR2+ subpopulation." (PMID 38391924, 2024).
mood disorder (1 paper, 2021). A cognitive disorder a disturbance in which the person's mood is hypothesized to be the main underlying feature. "Elevated CCL2 serum levels have also been found in patients with BD suggesting an impact of the CCR2/CCL2 axis in mood disorders." (PMID 33921690, 2021). "So far, the biological function of CCR2-expressing monocytes has been in the focus of studies regarding mood disorders." (PMID 33921690, 2021).
motor neuron disease (1 paper, 2017). "Furthermore, although CNS infiltrating CCR2+ monocytes are assumed to rather aggravate neurodegeneration/injury, this seems not that clear-cut: While they act deleterious e.g., in traumatic brain injury models, they are protective in motor neuron disease ALS mice." (PMID 28320442, 2017).
mycobacterial infection (1 paper, 2024). "Knockdown of miR-126 increases susceptibility to mycobacterial infection which can be independently reversed by targeting Tsc1/mTOR or ccr2 implicating macrophage function." (PMID 38307625, 2024). "Furthermore, double knockdown of miR-126 and either cxcl12a or ccr2 reduced cell death and from miR-126 knockdown alone, demonstrating that the Cxcl12/Ccl2/Ccr2 signalling axis is driving the miR-126 knockdown-associated increase in ineffective macrophage recruitment to mycobacterial infection." (PMID 38307625, 2024). "We link infection-induced miR-126 to Tsc1 via activation of the mTOR pathway and improved macrophage function because of regulation of a Cxcl12/Ccl2/Ccr2 signalling axis during the early stages of mycobacterial infection." (PMID 38307625, 2024).